PER2 (period circadian regulator 2)
Diseases named in the same sentence as PER2 in open-access papers (continued):
Sharing a sentence is not in itself a finding about the gene and the disease.
Obesity (38 papers, 2009 to 2025). Accumulation of substantial excess body fat. "Although the mechanisms underlying disease susceptibility is not fully understood, these results support an important role of PER2 genetic variants on obesity by regulating circadian gene expressions and functions." (PMID 35276838, 2022). "For example, PER2 is associated with abdominal obesity, psycho-behavioral factors, and attrition in the dietary treatment of obesity in humans." (PMID 35910841, 2022). "The Per2 mutation mice lack a glucocorticoid rhythm and diurnal feeding rhythm, which will develop obesity when fed a high-fat diet." (PMID 35910841, 2022). "The diurnal rhythm of neuroendocrine peptide αMSH is disrupted in Per2-deficient mice, which leads to circadian eating disorders such as night-eating syndrome, which gradually leads to obesity." (PMID 35371053, 2022). "The period circadian regulator 2 (Per2) gene is important for the modulations of rhythmic homeostasis in the gut and liver; disruption will cause metabolic diseases, such as obesity, diabetes, and fatty liver." (PMID 35910841, 2022). "Another study has shown that the deletion of Per2 causes glucocorticoid imbalance and leads to circadian eating disorders, such as night-eating syndrome and obesity in mice." (PMID 35910841, 2022). "The methylation status of CpG sites located in clock genes (Clock, Bmal1, and Per2) is associated with obesity, metabolic syndrome and weight loss." (PMID 31139087, 2019). "Obesity has also been associated with DNA methylation status of the clock genes Clock, Bmal1, and Per2." (PMID 31671625, 2019). "The effects of a mutation in the Per2 gene on obesity and metabolic profiles are, however, inconsistent and contradictory." (PMID 22934083, 2012). "Given the contradictory results on predisposition of Per2 mutant mice to obesity, we further characterized in this study the whole body glucose metabolic and vascular phenotypes of the Per2 mutant mice." (PMID 22934083, 2012). "Some genes in this subnetwork, such as Arntl, Dbp, Per1, and Per2, are known to associate with obesity traits, while other genes, such as Map3k6 and Tsc22d3, represent novel factors." (PMID 19463160, 2009). "Similarly, genetic mutation of core clock genes such as Bmal1, Clock, and Per2 leads to a dampened rhythm of food intake, and profound susceptibility to diet-induced obesity." (PMID 34557221, 2021). "We explored the hypothesis that decreased BMAL1 occupancy at the PER2 promoter in obesity might also be associated with changes of RNA polymerase II (RNA POLII) recruitment." (PMID 33888702, 2021). "Recently, CLOCK and PER2 polymorphisms have been linked to obesity and the metabolic syndrome." (PMID 30518396, 2018). "Thus, mice with Per2 gene mutation show altered glucose homeostasis and compromised insulin-stimulated NO release, independently of obesity." (PMID 22934083, 2012). "One study found that eating late slowed down the period circadian regulator 2 (PER2) rhythm, a protein that plays a critical role in regulating the circadian rhythm, present in adipose tissue, and these changes may increase the risk of obesity." (PMID 37752794, 2023). "After stratification by the genotypes of nine SNPs, the obesity risk according to the patterns was different according to the genetic variants of CLOCK, PER2, and CRY1." (PMID 35276838, 2022). "In conclusion, these findings suggest that macronutrient intake patterns were associated with obesity susceptibility, and the associations were different depending on the circadian clock genotypes of the CLOCK, PER2, and CRY1 loci." (PMID 35276838, 2022). "The GG genotype of PER2 rs2304672 in the VLFC showed greater risks for obesity and abdominal obesity." (PMID 35276838, 2022). "Obesity resulted in overall disruption of core clock genes (i.e., Bmal1, Clock, Rev-erbα/Nr1d1, Rev-erbβ/Nr1d2, Per1, Per2, Cry1, Cry2, Dbp and Rorα) in WAT." (PMID 35198059, 2022).
Obesity (continued). "After the genotype stratification of nine SNPs of circadian genes, the association between the FC ratio and obesity risk differed by the genetic variants of CLOCK, PER2, and CRY1." (PMID 35276838, 2022). "Intriguingly, the associations between macronutrient intake patterns and obesity risks were different depending on the genotypes of CLOCK rs11932595, PER2 2304672, and CRY1 rs3741892." (PMID 35276838, 2022). "Per2-KO mice lack a glucocorticoid rhythm and diurnal feeding rhythm, which can lead to obesity when fed a high-fat diet." (PMID 35371053, 2022). "In order to assess the oscillation of the peripheral clock in obesity, we generated lean and obese mice with a luciferase reporter for the core circadian clock component PER2." (PMID 35600313, 2022). "Recent studies reported that PER2 and PER3 polymorphisms are associated with diabetes and obesity, metabolic syndrome components." (PMID 35053018, 2021). "PER2 polymorphisms are negatively associated with diabetes, while PER3 polymorphisms are positively associated with obesity." (PMID 35053018, 2021). "We observed a decreased occupancy of RNA POLII at the PER2 promoter in obesity, consistent with the decreased PER2 expression in this condition." (PMID 33888702, 2021). "We showed that human OAPs display self-sustained circadian oscillations of PER2 with a lengthened period in obesity." (PMID 33888702, 2021). "The relationship between circadian clock dysregulation and macrophage proinflammatory activation in diet-induced obesity was evaluated in a Per1ldc/Per2ldc mutant mice, characterized by disruption of the clock genes Per1 and Per2." (PMID 33371208, 2020). "The differential impact of obesity on clock gene expression in the gonadal and subcutaneous adipose depots was most pronounced in Rev-erbα, Per1 and Per2 gene expression profiles." (PMID 27439882, 2016). "Obesity with adipose accumulation reduces the amplitude of circadian gene expression by decreasing the peak expression of clock genes such as Per1 and Per2 in WAT of genetically obese mice." (PMID 25615603, 2015). "We screened a commercially available metabolic peptide library (Obesity Peptide Library, Phoenix Europe GmbH; DE) for factors capable of resetting luciferase activity rhythms in organotypic liver slice cultures from Per2::LUC circadian reporter mice." (PMID 25821984, 2015). "To determine whether the absence of p110α modifies core clock genes in the context of HFD-induced obesity, we assessed gene expression of Bmal1, Cry1, Per2, and Rev-erbα." (PMID 40228209, 2025). "For example, expression of Per2 was decreased in astrocytes and can prevent neurotoxicity, therefore suggesting induction of neurotoxicity in neuronal cells in the condition of obesity." (PMID 39456952, 2024). "Interestingly, Per1, Per2, and Cry2 expression is unchanged in obesity but alters in pregnant obese rats." (PMID 39083072, 2024). "In 17 middle-aged subjects with obesity and normal glucose tolerance who underwent the procedure of the hyperinsulinemic-euglycemic clamp with continuous insulin infusion, the expression of core clock genes PER2 and PER3 was increased." (PMID 36432465, 2022). "Interestingly, by performing ChIP assays with antibodies directed against BMAL1, we found that BMAL1 binding to the E-box of PER2 was significantly decreased in obesity while NF-κB binding was increased." (PMID 33888702, 2021). "Although it is unknown how Per1 and Per2 controls macrophage activation in obesity, the authors suggested a disruption in the feedback regulation of CLOCK/BMAL1 protein complex." (PMID 33371208, 2020). "Taurine changed the expression of Clock, Rev-erbα and Per2, these effects of taurine could be tissue-dependent and peripheral clocks may be possible targets of this sulfonic acid during obesity." (PMID 27857215, 2016). "The discrepancy between our findings and others on obesity predisposition of Per2 gene disrupted mice is not clear." (PMID 22934083, 2012).
Obesity (continued). "While one study reports that mice with a Per2 gene disruption are prone to obesity, a recent study using mPer2Brdm1/Rev-Erbα−/− double mutant mice suggests that the Per2 gene is involved in hepatic glucose metabolism engaging a mechanism involving nuclear receptors." (PMID 22934083, 2012). "Besides, genetic variations in CLOCK, PER2, and CRY1 increase the risk of obesity." (PMID 39351493, 2024). "In the present study, conducted in a population of subjects with overweight/obesity, we observed an association between PM exposure measured in the week before the blood drawing and the methylation of circadian cycle genes (i.e., CLOCK, CRY1, CRY2, PER1, PER2, and PER3)." (PMID 33513987, 2021). "Abnormal expressions of PPP1CB and CSNK1E in obesity directly affect the core clock genes (PER1, PER2), and the accumulation of PERs and CRYs in the nucleus inhibits the transcription of CLOCK and BMAL1, disrupting energy homeostasis and leading to obesity." (PMID 39351493, 2024). "In summary, diet-induced obesity increases PAI-1 levels, but its transcription is suppressed by the Per2 gene." (PMID 36557311, 2022). "The present study aimed to evaluate the effects of PM2.5 and PM10 on the methylation profile of the clock genes ARNTL, CLOCK, CRY1, CRY2, PER1, PER2, and PER3 in a population of 200 women with obesity." (PMID 33513987, 2021). "Nocturnin in Per2-/- knockout mice have normal circadian mechanisms, although they display resistance to HFD-induced obesity and hepatic steatosis, which indicates that Nocturnin is downstream of the core circadian clock." (PMID 31139087, 2019). "In conclusion, our study shows that mice with a mutation in the circadian clock gene Per2 have compromised insulin signaling, associated with lower hepatic glycogen content and decreased vascular endothelial function, but no increased predisposition to obesity." (PMID 22934083, 2012). "However, DBP, PER2, and NFIL3, and in turn many of the downstream genes they govern, all display marked dysregulation in obesity." (PMID 35600313, 2022). "Adipocyte O-GlcNAcylation may promote obesity through its well-established target clock proteins, such as BMAL1, CLOCK and PER2." (PMID 34557221, 2021). "However, RNA POLII recruitment to PER2 E-box was reduced and also failed to display a significant rhythmic pattern in obese OAPs, which might explain the downregulation of PER2 expression and its altered rhythm in obesity." (PMID 33888702, 2021). "However, during our investigation we determined that hepatocyte-specific knockout of Per2 did not influence the body weight of mice, while TRF and Lip-1 did; and it is acknowledged that obesity itself is closely related to the prevalence and severity of NASH." (PMID 36285301, 2022). "In a time-course experiment with white adipose tissue biopsies from people with healthy weight or obesity or T2D, no variation in the rhythm and amplitude of core-clock (PER1, PER2, PER3, DBP, BMAL1, and CRY2), metabolic (PGC1), and clock-related (REVERB) genes could be observed in biopsy tissues." (PMID 37475884, 2023).
depression (31 papers, 2010 to 2025). "In this study, we found that anxiety, depression, and polymorphism at the rs934945 of the PER2 gene were risk factors for the development of sleep disorders." (PMID 40951374, 2025). "Intervention experiments targeting Per2 in intestinal epithelial cells confirmed its pivotal role, indicating that disturbances in peripheral rhythmicity contribute to the pathogenesis of depression linked to disruption in circadian system." (PMID 40847793, 2025). "PER2 rs2304672 genetic variants were previously associated with psychiatric disorders including bipolar disorder, depression, and diurnal preference." (PMID 35276838, 2022). "Alternatively, many mutations of circadian clock genes, including Per2, are correlated with depression- or mania-like behavior in mice." (PMID 25928892, 2015). "In summary, this study found that the occurrence of anxiety, depression, and sleep disorders is serious among mental workers in Xinjiang and that the polymorphisms of anxiety, depression, and PER2 genes and their interactions have an impact on the occurrence of sleep disorders." (PMID 40951374, 2025). "For mental workers carrying the PER2 rs934945 CT/TT genotype, prioritizing psychological support (e.g., cognitive-behavioral therapy for anxiety and depression) may mitigate sleep disorder risk by addressing the gene–environment interaction." (PMID 40951374, 2025). "Moreover, PER2 has been associated with sleep in adaptation to stress, and with depression vulnerability, in particular winter depression." (PMID 37761863, 2023). "Hence, our results showed that the rs934945 of the PER2 circadian gene was significantly associated with depression scores, whereas anxiety level was associated with COMT rs4680." (PMID 34330229, 2021). "Our study demonstrated a strong relationship between depression scores and cognitive impairment, sleep quality, marital status, fosaprepitant intake, and PER2 polymorphism, while anxiety scores were correlated to cognitive impairment, insomnia severity, fosaprepitant intake, and COMT polymorphism." (PMID 34330229, 2021). "Moreover, being married compared to single was also associated with lower depression scores, whereas higher PSQI scores (worse sleep quality) and having the PER2 AA variant genotype compared to GG were significantly associated with higher depression scores." (PMID 34330229, 2021). "For example, mutation in the Per2 gene alters the glutamatergic system and then leads to hyperglutamatergic states of the brain, resulting in increased preference for and voluntary consumption of alcohol, a common behavior in human depression patients." (PMID 23516567, 2013). "Recent research has elaborated on the neurobiological links between sleep disturbances and mood disorders, highlighting that circadian gene dysregulation (e.g., PER2 variants) may disrupt serotonin and cortisol pathways, which are also implicated in anxiety and depression." (PMID 40951374, 2025). "However, CRY2 and PER2 genetic variants, which might influence the evening and morning signals from the circadian pacemaker system, associate with depression vulnerability in humans." (PMID 21943377, 2011). "KD of CREB and/or Per2 using RNAi resulted in mania-like behaviors, while their overexpression in this region led to depression-like behaviors." (PMID 40011706, 2025). "In comparison, we found that knockdown of Per2 in CA1 leads to mania-like behavior, characterized by reduced depression- and impulsivity-like behaviors, consistent with their findings of Per2 KO in glia cells in mice." (PMID 40011706, 2025). "Another study demonstrated that melatonin rescued depressive symptoms in mouse model of depression by modulating Per2 circadian protein expression, maintaining astrocytic AQP4 polarization circadian rhythm, and restoring glymphatic function." (PMID 40917304, 2025).
depression (continued). "In 2021, Albrecht and colleagues revealed that mice with deletion of Per2 in glial cells showed reductions in both depression- and impulsivity-like behaviors." (PMID 40011706, 2025). "First, it is among the first to systematically investigate the interactive effects of anxiety, depression, and circadian clock gene polymorphisms (CLOCK, PER2, RORA) on sleep disorders in mental workers." (PMID 40951374, 2025). "Many studies indicate the involvement of Per1 and Per2 in patients with depression and bipolar disorder, with increasing reports highlighting the role of Per2 in BD." (PMID 40011706, 2025). "Knockdown of CREB or PER2 by shRNA in this region induced mania-like behaviors, whereas overexpression of those factors led to depression-like behaviors." (PMID 40011706, 2025). "On the other hand, the Per2 gene is involved in the regulation of sleep and the development of depression." (PMID 38239754, 2024). "In conclusion, we report a new mechanism whereby melatonin improves depression outcomes by regulating the expression of the circadian protein Per2, maintaining the circadian rhythm of astrocytic AQP4 polarization, and restoring glymphatic function." (PMID 37802998, 2023). "Period Circadian Regulator 2 (Per2)-deficient mice were immune to centrally administered LPS upregulation of CCL5 and thus less likely to suffer from neuroinflammation-induced depression-like behavior." (PMID 36614020, 2022). "The glial Per2 knock-out animals (GPer2) were tested for despair-based behavior, which is one of the important manifestations of depression." (PMID 34112905, 2021). "Disrupted rhythms of the Per2 gene, as well as other circadian genes, are correlated with major depressive disorder." (PMID 33509094, 2021). "Nevertheless, more studies are needed to explore the exact molecular effect of this SNP on PER2 transcription or protein expression/functionality and consequently the impact on the pathogenesis of depression in patients." (PMID 34330229, 2021). "In an experimental setting a reduction in the expression of per2 has been observed in the mouse hippocampus in a chronobiological animal model of depression whereas antidepressant pharmacotherapy increases levels of per2 in a time of day-dependent manner." (PMID 26679264, 2016). "SNPs of Per2, Npas2, and Bmal1 are linked to increased risk for SAD, while there is suggestive evidence of a link between Cry2 and depression." (PMID 26379559, 2015). "These clusters particularly involved genes related to regulatory subunits of cAMP-dependent protein kinases, such as PRKAR2A, cAMP-responsive element-binding pathway, circadian rhythms, such as CLOCK, ARNT1, CRY2, PER1, and PER2, and anxiety and depression, such as NOTCH1, NOTCH2 and ANK2." (PMID 41157308, 2025). "Therefore, overexpression of Per2 in CA1 region induced depression- and impulsivity-like behaviors and increased CREB levels in this region." (PMID 40011706, 2025). "Therefore, specific targeting on intestinal epithelial Per2 or tryptophan metabolism is a promising strategy to prevent CRD‐induced depression." (PMID 40847793, 2025). "The effects of anxiety, depression, and CLOCK, PER2, and RORA gene polymorphisms and their interactions on sleep disorders were further analyzed, to provide scientific references for the reduction of the risk of the occurrence of sleep disorders in mental workers." (PMID 40951374, 2025). "Clock gene Arntl, Nr1d1, Per2 and Cry2 expression in the hippocampus was increased in subjects with substance use disorder, while Arntl and Nr1d1 expression was decreased in subjects with major depression." (PMID 37441675, 2023). "Additionally, RANTES is a clock-controlled gene (CCG) involved in the clock-immunological mechanisms that contribute to the effects of Per2 on depression-like behavior induced by neuroinflammation." (PMID 37600668, 2023).